CLCP1 (Charcot-Leyden crystal protein pseudogene 1)
Gene: Processed pseudogene on chromosome 22 (17,424,388 to 17,424,775, reverse strand). Ensembl gene ENSG00000232305.
Diseases named in the same sentence as CLCP1 in open-access papers:
CLCP1 is named in the same sentence as 3 diseases in open-access papers, as found by Europe PMC text mining. Sharing a sentence is not in itself a finding about the gene and the disease. The quoted sentences say what the papers report.
gastric adenocarcinoma (1 paper, 2022). "Meanwhile, CLCP-1 and CLCP-2 in this study showed efficiently protected gastric adenocarcinoma (AGS) cells against H. pylori with the inhibition of the IL-8/NF-κB axis." (PMID 36433125, 2022).
cancer (1 paper, 2025). A tumor composed of atypical neoplastic, often pleomorphic cells that invade other tissues. "While mechanistic links to these different cancers are yet to be elucidated, it is likely that RHBDL2‐mediated cleavage of certain substrates such as CLCP1 may contribute to cancer progression." (PMID 41015904, 2025).
infection (1 paper, 2022). The state of being infected such as from the introduction of a foreign agent such as serum, vaccine, antigenic substance or organism. "When the cells were treated with 1000 μg/mL of CLCP-1 or CLCP–2, about a 35% reduction in the infection rate was observed in the post-treatment of cells while it had no inhibitory activity in the other two groups, suggesting that the CLCPs directly interact with H. pylori." (PMID 36433125, 2022).